MALAT1 (metastasis associated lung adenocarcinoma transcript 1)
Diseases named in the same sentence as MALAT1 in open-access papers (continued):
Sharing a sentence is not in itself a finding about the gene and the disease.
non-small cell lung carcinoma (continued). "For instance, MALAT1 RNA promoted migration and tumor growth of non-small cell lung cancer." (PMID 30285605, 2018). "The well-known lncRNA, metastasis-associated lung adenocarcinoma transcript 1 (MALAT-1), is highly expressed in early-stage non-small-cell lung carcinoma and could predict the metastasis and prognosis of these patients." (PMID 28112249, 2017). "Notably, several studies detected lncRNAs in body fluids as, for example: PCA3 in prostate cancer, H19 in gastric cancer, HULC in hepatocellular carcinoma, MALAT-1 in non-small cell lung cancer." (PMID 29246026, 2017). "For example, metastasis-associated lung adenocarcinoma transcript 1 (MALAT1), the earliest found cancer-related lncRNA, could promote cancer cells growth in non-small cell lung cancer (NSCLC)." (PMID 29383134, 2017). "Moreover, MALAT-1 has served as a metastatic and recurrence biomarker for non-small cell lung cancer and hepatocellular cancer." (PMID 27227769, 2016). "The lncRNA Metastasis-associated adenocarcinoma transcript 1 (Malat-1; also known as Nuclear Enriched Abundant Transcript 2, Neat2) was discovered in metastasizing non-small cell lung cancer and is highly expressed in most cell types and organs, including the heart." (PMID 26919721, 2016). "MALAT1 is firstly identified as a bio-marker for early stage non-small cell lung cancer." (PMID 27019196, 2016). "Metastasis-associated lung adenocarcinoma transcript 1(MALAT1), also known as NEAT2 (nuclear-enriched abundantly transcript 2), was found to be overexpressed not only in early-stage metastasizing non-small cell lung cancer (NSCLC) but also in breast, pancreas, colon, prostate, and liver cancers." (PMID 24908062, 2014). "MALAT1 expression is correlated with the prognosis of non-small cell lung cancer." (PMID 25422887, 2014). "The MALAT1 gene, or metastasis-associated lung adenocarcinoma transcript 1, was first associated with high metastatic potential and poor patient prognosis during a comparative screen of non-small cell lung cancer patients with and without metastatic tumors." (PMID 21489289, 2011). "The lncRNA metastasis-associated in lung adenocarcinoma transcript 1 (MALAT1), also known as nuclear enrichment autosomal transcript 2 (NEAT2), was originally identified as one of the most prominently overexpressed transcripts in metastatic non-small cell lung cancer tissues." (PMID 37653482, 2023). "In addition, it can increase MALAT1 expression in non-small cell lung cancer." (PMID 36316461, 2022). "The metastasis-associated lung adenocarcinoma transcript 1 (MALAT1), also known as nuclear-enriched transcript 2 (NEAT2), is a lncRNA consisting of more than 8700 nt located on chromosome 11q13 and discovered as a predictive marker for metastasis in early-stage, non-small cell lung cancer." (PMID 33799572, 2021). "Evidence of oncogenic activity of MALAT1, in the MALAT1 knockout model which unveiled that MALAT1 regulates the expression of metastasis-related genes which leads to metastasis of early-stage non-small cell lung cancer and is an efficient prognostic marker for the patient with poor survival rates." (PMID 32106407, 2020). "MALAT1 (metastasis-associated lung adenocarcinoma transcript 1), also known as NEAT2 (nuclear-enriched abundant transcript 2), is the first lcnRNA associated with a strong metastatic potential and poor prognosis in patients affected by non-small cell lung cancer." (PMID 25593996, 2014). "MALAT1 sponges miR-185-5p, leading to increased MDM4 expression, which supports cell proliferation in non-small cell lung cancer." (PMID 40002172, 2025). "In non-small cell lung cancer, the BMI1/MALAT1 axis sequesters miR-145-5p to support tumor survival." (PMID 40623983, 2025). "In non-small cell lung cancer (NSCLC), METTL3 directly promotes YAP translation and increases YAP activity by regulating the MALAT1-miR-1914-3p-YAP axis, leading to drug resistance and metastasis." (PMID 38627760, 2024).
non-small cell lung carcinoma (continued). "LncRNA MALAT1 also known as NEAT-2 (nuclear enriched abundant transcript-2) or LINC00047, was initially characterized by Ji and coworkers (2003) in non-small cell lung cancer, it acts as a proto-oncogene and is located at 11q13." (PMID 38739668, 2024). "For example, in non-small cell lung cancer, METTL3-mediated m6A methylation increased the stability of YAP mRNA by regulating Malat1-miR-1914-3p-Yap axis-induced chemotherapy resistance." (PMID 36932427, 2023). "For example, lncRNA MALAT1 promotes NET formation, and NETs promote non-small cell lung cancer (NSCLC) metastasis by suppressing lncRNA MIR503HG expression to activate the inflammasome pathway." (PMID 37980632, 2023). "Combination effect of METTL3 with YTHDF3 can improve the stability of MALAT1 and increase the expression of MALAT1, thus increase the stability of YAP mRNA by regulating MALAT1-miR-1914-3p-YAP axis in non-small cell lung cancer." (PMID 35022030, 2022). "MALAT1 was named based on its clinical importance in metastasis anticipation, its high expression in metastatic samples, and survival in early-phase non-small cell lung carcinoma (NSCLC)." (PMID 36163080, 2022). "Also known as non-coding nuclear-enriched abundant transcript 2 (NEAT2), MALAT1 was initially identified as a prognostic marker for metastasis and poor patient survival in non-small cell lung carcinoma (NSCLC)." (PMID 32708561, 2020). "For stage I non-small cell lung cancers (NSCLC), high MALAT1 expression levels have been described to correlate with metastasis." (PMID 23717670, 2013). "Additionally, the MALAT1-miR-1914-3p-YAP axis is regulated by METTL3-initiated m6A mRNA methylation, which enhances YAP activity and directly stimulates YAP translation in non-small cell lung cancer (NSCLC)." (PMID 38125749, 2023). "Also, in non-small-cell lung cancer, IGF2BP2 enhances the proliferation of tumor cells by binding to the oncogenic MALAT1 lncRNA and increasing its stability." (PMID 35664076, 2022). "Numerous researches already elucidated MALAT1 induces proliferation, invasion and migration through miRNA-mediated manner in colorectal cancer (CRC), breast cancer, gallbladder cancer, non-small cell lung cancer (NSCLC), and oral squamous cell carcinoma (OSCC)." (PMID 35697671, 2022). "METTL3 relies on YTHDF1/3 and eIF3B to promote yes-associated protein (YAP) mRNA translation and increases YAP mRNA stability by modulating the MALAT1–miR-1914-3p–YAP axis, thereby inducing treatment resistance and metastasis in non-small cell lung cancer (NSCLC)." (PMID 32398132, 2020). "MALAT1 was first identified as a factor indicating high metastatic potential and poor prognosis in a study of gene expression differences in stage I non-small-cell lung cancer (NSCLC) with/without metastasis." (PMID 26420912, 2015). "In addition, increased expression of MALAT-1 has been recently shown to be an independent prognostic factor for HCC following liver transplantation and non-small cell lung cancer." (PMID 23680400, 2013). "For instance, MALAT1, also known as NEAT2, was found upregulated in non-small cell lung cancer tissues and could be served as an early prognostic biomarker; lncRNA HOTAIR had been explored as a potential biomarker on the detection of hepatocellular carcinoma relapse." (PMID 34727886, 2021). "Importantly, programmed death-ligand 1 (PD-L1) was found to arrest metastasis of non-small cell lung cancer cells; its expression is directly affected by miR-200a and regulated by the MALAT1/miR200a/PD-L1 negative feedback loop." (PMID 35011635, 2021). "Metastasis associated lung adenocarcinoma transcript 1 (MALAT1), which is also known as NEAT2 (noncoding nuclear-enriched abundant transcript 2) and was first identified in 2003 in non-small cell lung cancer, is one of the initially identified long non-coding RNAs associated with human diseases." (PMID 30871555, 2019).
non-small cell lung carcinoma (continued). "Metastasis associated lung adenocarcinoma transcript 1, (MALAT-1, 22 ORESTES) is a conserved long non-protein-coding RNA (>8,000 nucleotides (nt)) of unknown function that is highly expressed in numerous healthy organs and overexpressed in metastatic non-small cell lung carcinomas." (PMID 17562024, 2007).
hepatocellular carcinoma (210 papers, 2012 to 2026). A malignant tumor that arises from hepatocytes. "Intriguingly, MALAT1 wasshown to be enriched in the mitochondria of hepatocellular carcinoma and associatedwith epigenetically altering mitochondrial DNA." (PMID 39513696, 2024). "Previous studies have reported that the MALAT1 polymorphisms were associated with cancer development, carcinogenesis and prognosis in various cancers such as hepatocellular carcinoma, cervical cancer, oral squamous cell carcinoma, and prostate cancer." (PMID 38517388, 2024). "MALAT1, a long-non-coding RNA associated with tumor metastasis and invasion in lung cancer and hepatocellular carcinoma (HCC), has also been found to be enriched in EVs from cervical carcinomas and breast cancer cells." (PMID 35814444, 2022). "Mitophagy events were significantly reduced after the knockdown of MALAT1; as observed in MALAT1-deficient hepatocellular carcinoma cells, mitophagy proteins, notably PINK1, p62, NDP52, BNIP3, and LC3, were decreased in regulation." (PMID 36642914, 2022). "In hepatoma cells, the nuclear genome-encoded lncRNA MALAT1 is abnormally transported into the mitochondria." (PMID 34568319, 2021). "At the same time, studies also showed that MALAT1 SNPs affected the susceptibility and progression of diseases including hepatocellular cancer, lung adenocarcinoma and pulmonary arterial hypertension." (PMID 32238151, 2020). "For example, metastasis associated lung adenocarcinoma transcript 1 (MALAT1), a well-known oncogene, has been linked with a variety of cancers such as pancreatic cancer, prostate cancer, hepatocellular carcinoma and thyroid cancer." (PMID 33318305, 2020). "For example, the MALAT1 rs619586 G variant was associated with a decreased risk of hepatocellular carcinoma and colorectal cancer." (PMID 31024342, 2019). "The long noncoding (lnc)RNA, metastasis-associated lung adenocarcinoma transcript 1 (MALAT1), plays a crucial role in the development of hepatocellular carcinoma (HCC)." (PMID 31500187, 2019). "The long non-coding RNA (lncRNA) metastasis associated lung adenocarcinoma transcript 1 (MALAT1) was recently discovered to interfere with SIRT1 activity in hepatocellular cancer." (PMID 30319549, 2018). "Another lncRNA, MALAT-1 (metastasis associated lung adenocarcinoma transcript 1) is overexpressed in many different cancer types, including lung, breast, colon, prostate, pancreatic, and hepatocellular carcinomas." (PMID 25288503, 2014). "Several lncRNAs contain SNPs such as rs7763881 in highly upregulated in liver cancer long noncoding RNA (HULC) and rs619586 in MALAT1 which are reportedly associated with decreased hepatocellular carcinoma risk." (PMID 23843741, 2013). "The long noncoding RNA (lncRNA) MALAT1 (metastasis-associated lung adenocarcinoma transcript 1), typically enriched in the nucleus, was found to be aberrantly localized in the mitochondria of hepatoma cells." (PMID 40655944, 2025). "LncRNA HULC (Highly Upregulated in Liver Cancer) and lncRNA MALAT1 (Metastasis-Associated Lung Adenocarcinoma Transcript 1) have been found to be significantly upregulated in hepatocellular carcinoma patients, indicating their potential role in liver cancer progression and as diagnostic indicators." (PMID 39211780, 2024). "In another type of ncRNA, namely, long ncRNAs (lncRNAs), metastasis-associated lung adenocarcinoma transcript 1 (MALAT1) has been suggested to promote hepatocellular carcinoma (HCC) cell proliferation, migration, and invasion by epigenetically regulating mtDNA-encoded ETC-related genes." (PMID 37298366, 2023). "Additionally, the lncRNA MALAT1 (Metastasis-associated lung adenocarcinoma transcript 1), is up-regulated and exerts oncogenic activity in hepatocellular carcinoma (HCC)." (PMID 35427215, 2022).
hepatocellular carcinoma (continued). "Metastasis-associated lung adenocarcinoma transcript 1 (MALAT1) is a functional lncRNA that is located on chromosome 11q13 and was reported to be involved in multiple cancers including osteosarcoma, hepatocellular carcinoma, and esophageal squamous cell carcinoma." (PMID 26307974, 2015). "Metastasis-associated lung adenocarcinoma transcript 1 (MALAT1) is found in high amounts in hepatocellular carcinoma cell (HCC) mitochondria." (PMID 35740618, 2022). "As a long non-coding RNA (lncRNA) and a transcriptional regulator, Metastasis associated lung adenocarcioma transcript-1 (MALAT-1) has been reported to be associated with proliferation and metastasis of hepatocellular carcinoma (HCC)." (PMID 31350456, 2019). "For example, in hepatocellular carcinoma, MALAT1 upregulates SMAD5 expression by sequestering miR‐142‐3p, which promotes epithelial–mesenchymal transition and enhances tumor cell proliferation and invasiveness." (PMID 41584724, 2026). "In hepatocellular carcinoma, MALAT1 localizes to mitochondria and interacts with multiple mitochondrial DNA (mtDNA) loci (D-loop, COX2, ND3, CYTB)." (PMID 41199749, 2025). "In hepatocellular carcinoma (HCC), betulinic acid reduces the levels of metastasis-associated lung adenocarcinoma transcript 1 (MALAT1), a long non-coding RNA that acts as a “sponge” for miRNA-22-3p." (PMID 41226811, 2025). "In accordance, MALAT1 is shown to act as a nucleus-to-mitochondria epigenetic messenger in hepatocellular carcinoma cells, and its suppression induces alterations in the CpG methylation of mtDNA and in mitochondrial transcriptomes." (PMID 40650203, 2025). "Since its discovery, the MALAT1 has been extensively studied in various types of cancer, such as breast, cervical, colorectal, gallbladder, lung, ovarian, pancreatic, prostate, and hepatocellular carcinoma." (PMID 40128064, 2025). "One study conducted in hepatocellular carcinoma patients confirmed a significant correlation between the expression of MALAT1 and levels of AST (p = 0.001) and hemoglobin concentration (p = 0.009)." (PMID 40150019, 2025). "MALAT1 is a lncRNA that has been reported to serve as an inhibitor of miR-613 in hepatocellular carcinoma cells, wherein this miRNA can drive tumor metastasis via the peripheral vascular system." (PMID 40549746, 2025). "As for MRLs involved in mitophagy, knockdown lncRNA MALAT1 can reduce mitophagy in hepatocellular carcinoma." (PMID 38218807, 2024). "In line with prior studies, Malat1 has been shown to boost the migration and invasion abilities in hepatocellular carcinoma through its interaction with miR‐124‐3p." (PMID 39491316, 2024). "At the same time, MALAT1 regulates the miR-3129-5p/Nova1 axis to reduce the sensitivity of hepatocellular carcinoma to adriamycin." (PMID 36793374, 2023). "In gallbladder cancer and hepatocellular carcinoma, it has been reported that MALAT1 plays an oncogenic role as a promoter of proliferation and metastasis through activating the MAPK-pathway." (PMID 37235843, 2023). "A recent study indicated that MALAT1 is located in mitochondria in HepG2 hepatocellular carcinoma (HCC) cells." (PMID 37298366, 2023). "Expanding the analysis to other cancer types shows that MALAT1 expression is also downregulated in hepatocellular carcinoma and squamous cell carcinoma of the lung." (PMID 37235843, 2023). "MALAT1 knockdown in hepatocellular carcinoma cells inhibits VEGF-A levels and skews macrophages toward the M1 subtype." (PMID 37860007, 2023). "The lncRNA MALAT1 is located in the mitochondria of hepatoma cells, regulating the energy metabolism of cancer cells and affecting tumor phenotype." (PMID 36672487, 2023). "For instance, MALAT1 upregulated SMAD5 expression by reducing miR-142-3p expression in hepatocellular cancer, which facilitates cell growth and EMT23." (PMID 36635290, 2023). "In the area of arsenic exposure, the levels of MALAT1 expression were increased in hepatocellular carcinoma (HCC) patients." (PMID 36139662, 2022).